TNFAIP2 (TNF alpha induced protein 2)
Diseases named in the same sentence as TNFAIP2 in open-access papers (continued):
Sharing a sentence is not in itself a finding about the gene and the disease.
cancer (continued). "TNFAIP2, which can be induced by treatment of TNF-α that with miR-184 can directly target TNFAIP2 in carcinoma (NPC) tissues, and is closely related to invasion and metastasis and poor survival in NPC patients." (PMID 25888093, 2015). "As a target gene of retinoic acid in acute pro-myelocytic leukemia and other cancers, TNFAIP2 plays an important role in controlling of apoptosis." (PMID 25383966, 2014). "The TNFAIP2 expression can exhibit variation across different cancer types." (PMID 39015503, 2024). "We hypothesized that TNFAIP2 protected cancer cells from cisplatin cytotoxicity in a ROS/JNK pathway-inhibited manner." (PMID 37525222, 2023). "Dysregulation of TNFAIP2 and its oncogenic role have been reported in a variety of cancers." (PMID 36243694, 2022). "The expression of TNFAIP2 is frequently abnormal in human cancers and infectious diseases." (PMID 36140707, 2022). "Hence, the mRNA expression and prognostic values of TNFAIP2 was comprehensively explored in pan-cancers by utilizing public datasets in this study." (PMID 36243694, 2022). "Nonetheless, TNFAIP2 is not well-recognized in cancer, and the hotspot or other mutations in the gene have not been reported before." (PMID 34900699, 2021). "RARRES1 and TNFAIP2 have been commonly investigated in many cancers." (PMID 33587010, 2021). "TNFAIP2 might promote cancer cell proliferation, invasion and metastasis via the NF-κB, retinoic acid, and Kruppel-like factor 5 signalling pathways." (PMID 34344926, 2021). "In addition, previous studies reported the abnormal expression of PGF and TNFAIP2 in human cancer, including CC." (PMID 33109108, 2020). "The expression of TNFAIP2 is frequently abnormal in human cancers and in infectious diseases." (PMID 30145807, 2018). "Small molecular inhibitors, anti‐TNFAIP2 siRNAs, or monoclonal antibodies of TNFAIP2 might develop into anti‐cancer drugs." (PMID 30145807, 2018). "Expression of TNFAIP2 was found to be abnormal in cancers, bacteria and virus infectious diseases." (PMID 30145807, 2018). "Therefore, it is necessary to develop reagents and methods, especially standard IHC techniques, to accurately and conveniently measure changes in TNFAIP2 protein expression in cancer specimens." (PMID 30145807, 2018). "Researchers have suggested that TNFAIP2 may play multiple roles in the development of cancer and may be particularly closely related to tumor metastasis." (PMID 25888093, 2015). "Firstly, the role of TNFAIP2 in carcinogenesis may vary in different cancers." (PMID 36243694, 2022). "It remains to be investigated whether the chronic activation of inflammatory signaling during aging and carcinogenesis would lead to chronic induction of Tnfaip2/Exoc3‐driven lipid metabolism in tissue‐resident stem cells and how this would affect tissue maintenance and cancer initiation." (PMID 33300287, 2021). "Integrin β4, relying on the regulation of TNFAIP2 and IQGAP1, effectively activated RAC1, promoting the migration of TNBC cells while enhancing the resistance of cancer cells to DNA damage-related therapies." (PMID 40830812, 2025). "In AML cells THP-1 and U937, knockdown TNFAIP2 led to inhibition of cellar inhibition, cell cycle arrest and increase of apoptosis, indicated the oncogenic function of TNFAIP2 in AML, which was consistent in other type of cancers." (PMID 36243694, 2022). "However, the transcript levels of TNFAIP2 and TNFAIP8L2 were not significantly different between cancer samples and normal samples." (PMID 34344926, 2021).
tumor (23 papers, 2015 to 2025). "To determine if TMCs are important for tumor cell extravasation, we used macrophages with reduced levels of endogenous M-Sec (TNFAIP2), which causes a defect in tunneling nanotube formation." (PMID 37046751, 2023). "TNFAIP2 plays a significant role in tissue development, angiogenesis, inflammatory response, tumor growth and drug resistance." (PMID 39532855, 2024). "TNFAIP2 is abnormally highly expressed in a variety of tumor cells, including TNBC, nasopharyngeal carcinoma, malignant glioma, uroepithelial carcinoma, and esophageal squamous cell carcinoma, and is associated with poor prognosis." (PMID 37787041, 2023). "We found that TNFAIP2 was upregulated in advanced-stage patients, suggesting its tumor-promoting role." (PMID 37525222, 2023). "More importantly, TNFAIP2 depletion further decreased tumor volume when mice were treated with EPI and BMN." (PMID 37787041, 2023). "Further in vitro studies are warranted to functionally validate the significance of TNFAIP2 in AML tumor immunology." (PMID 36243694, 2022). "By large-scale data mining, our study indicated that TNFAIP2 was differentially expressed across different normal and tumor tissues." (PMID 36243694, 2022). "Expression of the Tnfaip2 gene is induced in response to Tnf, which plays a pivotal role in tumor formation and growth." (PMID 30275866, 2018). "Overexpression of Tnfaip2 significantly promotes tumor cell proliferation, and silencing of Tnfaip2 suppresses proliferation." (PMID 30275866, 2018). "Other published targets, linked to an involvement in the regulation of apoptosis and tumour invasion, include BCL2, CDC25A and TNFAIP2." (PMID 28736583, 2017). "TNFAIP2 may involve in the tumour immunomodulation, thus playing a role in inducing cell differentiation and other biological functions." (PMID 38271140, 2024). "Moreover, the combination of si-Tnfaip2 and cisplatin resulted in the most significant tumor inhibition and apoptosis induction effects." (PMID 37525222, 2023). "Additionally, TNFAIP2 mRNA expression in 1457 cell lines derived from 26 tumor types in the CCLE database were also analyzed." (PMID 36243694, 2022). "In addition, TNFAIP2 also regulates the apoptosis of tumor cells and is considered to be a target gene for retinoic acid in acute promyelocytic leukemia." (PMID 32793480, 2020). "Our results indicated that GZZSZTW significantly increased the expression levels of multiple genes involved in promoting cell proliferation, most of which are highly expressed in tumor cells, such as Tnfaip2, Chi3l1, Tnf, Pfkfb3, Sox8, Jag1, Mafb, Pla2g7, Hnrnpa1, and E2f3." (PMID 30275866, 2018). "With TNFaip2 as a primary response gene of TNFα and highly expressed in immune cells, the decrease of TNFaip2 in CHRNA7KO BMDCs could be associated with a loss of responsiveness to inflammatory molecules in the tumor microenvironment of a CHRNA7KO host." (PMID 40653990, 2025). "Moreover, CD163, TNFAIP2, and SAMSN1 displayed a robust association with survival outcomes that remained significant independently of key clinical parameters such as gender, age at diagnosis, tumor content (%), and disease stage." (PMID 39015503, 2024). "In addition, TNFAIP2 can activate ras-related C3 botulinum toxin substrate 1 and cell division cycle 42, which promote the proliferation, migration and cytoskeletal remodeling of tumor cells." (PMID 37525222, 2023). "Knockout of the M-Sec (TNFAIP2) gene impaired TMC formation, reducing macrophage-tumor cell interactions and decreasing distant metastasis, suggesting that such direct contacts are critical for tumor cell transendothelial migration and metastasis." (PMID 40995371, 2025). "Involving other clinical parameters such as age at diagnosis, gender, and tumor content (%) in Cox survival analysis model 2, ITGAX,SAMSN1, TNFAIP2 and CD163 showed significant values." (PMID 39015503, 2024).
tumor (continued). "Our previous studies demonstrated that TNFAIP2 is a KLF5 downstream target gene in response to TNFα and TNFAIP2 knockdown inhibited HCC1806 xenograft tumor growth." (PMID 39532855, 2024). "However, the potential contribution of TNFAIP2 to tumor angiogenesis remains unknown." (PMID 39532855, 2024). "M-Sec (TNFAIP2) is an important regulator of TNT-like membranous connections in macrophages, tumor cells, and other cell types." (PMID 37046751, 2023). "An increase in TNFAIP2, ICAM1, and ITGA5 expression pointed to a possible TREM1- and HuR-dependent formation of tertiary structures between tumor and myeloid-derived cells within the inflammatory peri-necrotic areas." (PMID 36249290, 2022). "The results showed that TNFAIP2 overexpression had no influence on either tumor weight or volume, while it significantly diminished the treatment effect of cisplatin." (PMID 37525222, 2023). "TNFAIP2 is a novel gene induced by TNF-α and can regulate inflammatory and tumor angiogenesis." (PMID 32793480, 2020). "Interestingly, the tumor lesion area was reduced in the Tnfaip2 knockdown group, but this effect was not significant when TNFAIP2 was overexpressed in a xenograft nude mouse model." (PMID 37525222, 2023). "Normal and tumour tissues from such patients were analysed by qRT-PCR for the following 12 genes; six from RNA-seq: CLDN1, MAGEB2, CD24, CEACAM6, IL1B and ISG15 and six from RNA-seq and proteomics cross-linking: AKR1C3, TNFAIP2, RAB7A, LGALS3BP, PSCA and SSRP1." (PMID 36428603, 2022). "Notably, targeting Tnfaip2 in healthy mice (rather than xenograft tumor models) could also restrict tumor growth." (PMID 37525222, 2023). "Moreover, qRT-PCR verified seven apoptosis-related genes (APP, DOCK8, IFI44, MDK, SLC27A2, TNFAIP2, WNT5A) with at least 2 fold changes by means of 2−ΔΔCt method, finding that APP, SLC27A2 and WNT5A had a low expression, while DOCK8, IFI44, MDK, TNFAIP2 had a high expression in ccRCC tumor tissues." (PMID 33748185, 2021).
infection (7 papers, 2015 to 2024). The state of being infected such as from the introduction of a foreign agent such as serum, vaccine, antigenic substance or organism. "In resistant birds, two genes affiliated with the interferon activation pathway were increased upon infection, TNF alpha induced protein 2 (TNFAIP2) and interferon induced protein with tetratricopeptide repeats 5 (IFIT5)." (PMID 37005445, 2023). "Because TNFAIP2 expression was upregulated in AML patient samples and associated with poor survivals, we explored the biological role of TNFAIP2 in AML by establishing stable TNFAIP2 knockdown AML cell lines THP-1 and U937 cell lines via lentivirus infection." (PMID 36243694, 2022). "On the other hand, the caIBDV arrested the host's apoptotic process by inducing the expression of apoptosis inhibitors including NFKBIA/Z, TNFAIP2/3 and ITA at the first 12 hours of infection." (PMID 26053856, 2015). "Thus, after infection, monocytes from LPD-fed mice had decreased levels of Tnfaip2, whose expression is regulated by TNFα and other proinflammatory stimuli like IL1β and LPS via NFκB activation." (PMID 39349819, 2024).
inflammation (1 paper, 2021). Aberrant reaction of the microcirculation characterized by movement of fluid and leukocytes from the blood into extravascular tissues. "LMAN1 has also been associated with coagulation, and both TNFAIP2 and HLA-DQB1 are associated with vascular inflammation." (PMID 33961016, 2021).
TNFAIP2 also shares sentences with these, for which no sentence is quoted: infectious disease (5 papers); esophageal squamous cell carcinoma (4); squamous cell carcinoma (3); bladder cancer (2); bladder urothelial carcinoma (2); inflammatory bowel disease (2); lymphoma (2); pancreatic adenocarcinoma (2); thymoma (2); adrenocortical carcinoma (1); autoimmune myocarditis (1); bacterial infection (1); breast invasive carcinoma (1); cervical squamous cell carcinoma (1); colon adenocarcinoma (1); colorectal cancer (1); COVID-19 (1); diffuse large B-cell lymphoma (1); disc degeneration (1); endocervical adenocarcinoma (1); esophageal carcinoma (1); esophagus cancers (1); lung adenocarcinoma (1); lung squamous cell carcinoma (1); lymph node metastasis (1); meningioma (1); mesothelioma (1); myeloid leukaemia (1); Obesity (1); ovarian serous cystadenocarcinoma (1).
A further 11 diseases each share a sentence with TNFAIP2 in 1 paper.